EZR (ezrin)
Diseases named in the same sentence as EZR in open-access papers (continued):
Sharing a sentence is not in itself a finding about the gene and the disease.
cancer (continued). "Ezrin has been shown to be a key regulator of cellular migration in multiple human cancer lines." (PMID 36899847, 2023). "EZR plays a key role in promoting the invasion and metastasis of malignant tumors." (PMID 37715200, 2023). "Ezrin has also received a large amount of interest in relation to its ability to promote cancer cell invasion and metastasis with the inhibition of its phosphorylation at Thr567 being seen as one avenue to prevent its activation and reduce cancer cell invasiveness as well as potential metastasis." (PMID 36899847, 2023). "Meta-analysis suggests that ezrin is a potential prognostic marker in cancer patients." (PMID 35328667, 2022). "Moreover, ezrin is regarded as an important target protein in cancer diagnosis and therapy because it is a key protein involved in cancer progression and metastasis, and its high expression is linked to poor survival in many cancers." (PMID 35328667, 2022). "Furthermore, the ectopic expression of phosphomimetic forms of ezrin promotes cancer progression and metastasis in vitro and in vivo." (PMID 36355541, 2022). "ERM proteins (Ezrin, Radixin, Moesin) are known to provide a physical connection between actin cytoskeleton and plasma membrane, thereby participating in cell migration and cancer metastasis." (PMID 36175399, 2022). "The phosphorylated ezrin (p-Ezrin) could interact with F-actin, and subsequently regulates cell motility, polarity and adherence which are closely related to cancer metastasis." (PMID 35173550, 2022). "As expected, our results revealed that the knockdown or inhibition of Ezrin effectively restored cell sensitivity to antiestrogens, and subsequently reversed the ERα signaling in endocrine-resistant cancer cells, implying the potential role of Ezrin as a target in overcoming endocrine resistance." (PMID 36386154, 2022). "In this work, we finally interrogated how CIGB-300 could impact some cancer poor-prognosis markers such as Ezrin, c-Myc and Fibrillarin in an NCI-H460 cell model." (PMID 36672551, 2022). "Given that Ezrin phosphorylation necessitates the activation of the p38 MAP kinase, we further investigated whether CD44-Ezrin complexes could induce cancer cells dissemination through p38 activation." (PMID 35680853, 2022). "There are also many cancer drugs targeting ezrin in natural compounds." (PMID 36355541, 2022). "Interestingly, cells with MST4 overexpression showed an increase in phosphorylation of MST4 substrate protein Ezrin, a protein activating cancer cell invasion, and GSK3β, a protein regulating EMT progression." (PMID 36552828, 2022). "The role of the WWOX-Ezrin complex in cancer has yet to be determined." (PMID 33946771, 2021). "Here, we describe a novel mode of cooperation of EGFR and FAK signalling, which converge on ezrin, and has provided the opportunity to investigate possible treatments such as targeting FAK and/or ezrin in combination with EGFR to overcome EGFR TKI resistance in cancer cells." (PMID 34375550, 2021). "Given that ERM proteins globally dissociate from the PM in aggressive cancer cells, we reasoned that membrane-targeted active ezrin (MA-ezrin) could rescue decreased PM tension." (PMID 34635648, 2021). "Furthermore, emerging evidence has demonstrated that during cancer development, the protein expressions of ezrin especially in the plasma membrane of cancer cells are elevated, leading to cancer progression, invasion, and metastasis." (PMID 34577564, 2021). "Similar to KI67, EZRIN has been used as a marker for cancer metastasis and chemotherapy response." (PMID 34071614, 2021). "Notably, cancer cell treatment with Iru or Ori induced a marked reduction of Akt phosphorylation, and the same effect was previously observed when an Ezrin down-regulation occurred." (PMID 33003361, 2020). "Thus, ezrin contributes to the basal and stimulus-dependent expression of tumorigenic factors in macrophages, but the nature of the stimulus in cancer cell CM remains to be elucidated." (PMID 33086476, 2020).
cancer (continued). "In fact, although the two diterpenes only differ because of the position of a single hydroxyl group, and therefore their activities were quite similar, Iru showed a higher affinity towards Ezrin in cancer cells and was more efficient in reducing cancer cell mobility and invasion than Ori." (PMID 33003361, 2020). "Ezrin knockdown reduced the stimulated transmigration by about 60% for CM from both cancer cells." (PMID 33086476, 2020). "After systemic analysis of prognosis-related miRNA targets in those cancer-related signal pathways, we found that two targets ezrin (EZR) and hematopoietic cell-specific Lyn substrate 1 (HCLS1) had the potential prognostic characteristics with CRC regarding over survival (OS) or recurrence." (PMID 32293320, 2020). "Therefore, direct inactivation of Ezrin by the small molecule inhibitors should provide a new strategy for metastatic treatment in many cancers." (PMID 33240887, 2020). "All the existing studies, taken together, highlighted the fact that Ezrin may serve as a potential therapeutic target in cancer." (PMID 33240887, 2020). "Ezrin is correlated with poor prognoses in these cancer patients." (PMID 33240887, 2020). "Therefore, targeting Ezrin phosphorylation and actin binding activity provides a new therapeutic direction for clinical cancer interventions." (PMID 33240887, 2020). "Moreover, since Ezrin has been shown to modulate Matrix Metalloproteinases activity in cancer cells, we examined the effect of the two diterpenes on either MMP-9 or MMP-2 activity." (PMID 33003361, 2020). "Dynamic rearrangement of the cytoskeleton is crucial to cell mobility and migration in metastasis, and ezrin, radixin, and moesin are important membrane-cytoskeletal crosslinkers which are suggested to play vital roles in cancer progression, especially ezrin and moesin." (PMID 33072782, 2020). "This could suggest that decreasing migration capacity of cancer cells in the presence of ezrin inhibitor could play a more prominent role in reducing distant metastasis than contribution from alterations in peritumoral vascular density in our model." (PMID 30678714, 2019). "However, the efficacy of pharmacological inhibition of ezrin in blocking cancer cell migration and metastasis remains unexplored in BC." (PMID 30678714, 2019). "Ezrin, a member of the ezrin–radixin–moesin (ERM) family of actin cytoskeleton–plasma membrane linker proteins, is involved in multiple aspects of cancer cell migration and its overexpression has been associated with poor prognosis in a variety of solid tumors." (PMID 30678714, 2019). "Therefore, one can predict that a decrease in cancer cell motility in ezrin inhibitor-treated mice would contribute to the reductions in LN and lung metastatic burden observed in this study." (PMID 30678714, 2019). "Given that angiogenesis is crucial for the metastasis and progression of cancer, we explored whether Ezrin has a role in BC angiogenesis." (PMID 30804430, 2019). "Together, these findings prompted us to examine whether pharmacological inhibition of ezrin could have therapeutic benefits by suppressing the spread of highly metastatic cancer cells from lymph node micrometastases." (PMID 30678714, 2019). "Ezrin plays a critical role in maintaining epithelial integrity and in focal adhesion and invadopodia turnover, both key processes in metastatic progression of cancer cells." (PMID 30678714, 2019). "Ezrin is related to increased invasiveness of tumor cells and poor survival in several cancers." (PMID 30285121, 2018). "Additionally, Ezrin was transiently inhibited in cancer cells by transfecting with siRNA plasmid against Ezrin." (PMID 30224826, 2018). "Several studies disclosed that ezrin proteins play an important role in the development of cancer." (PMID 28355349, 2017). "In contrast, when ezrin was overexpressed, cancer cells had higher ability to invade and migrate." (PMID 28061797, 2017).
cancer (continued). "In addition, a recent study indicated that ezrin binds to another actin-binding protein, cortactin, in cancer cells to promote formation of podosomal rosettes, which digest underlying fibronectin and promote invasion." (PMID 29291001, 2017). "Ezrin overexpression promotes migration and invasion of cancer cells, and ezrin appears to allow metastatic cells to overcome a number of stresses experienced during the metastatic cascade, most notably, the stress experienced as cells interact with microenvironment of the secondary site." (PMID 27622508, 2016). "Ezrin and p130Cas are both cytosolic structural proteins that play an important role in signaling pathways affecting the cytoskeleton and regulating cell motility and proliferation, and are involved in cancer dissemination." (PMID 27622508, 2016). "Ezrin also plays a crucial role in morphogenesis, and an absence of Ezrin was associated with morphological changes in cancer cells through actin cytoskeleton remodeling." (PMID 26933912, 2016). "As seen with Ezrin and Mesothelin, ENOA has been linked to cell migration and cancer metastasis." (PMID 26840568, 2016). "Interestingly, overexpression of T567D Ezrin, a phospho-mimicking Ezrin mutant, promoted the cancer cell proliferation, while an overexpression of wild-type Ezrin showed inhibitory effects on cell proliferation." (PMID 26202611, 2015). "However, the results about the prognostic value of Ezrin expression in cancer patients remain inconsistent." (PMID 26632332, 2015). "However, although much is known about the functional role of ezrin in cancer development and progression, the biochemical mechanism of ezrin up-regulation has not been thoroughly investigated." (PMID 25915860, 2015). "Furthermore, the ERM proteins are also found to be dynamically regulated during cancer progression, with Ezrin being upregulated during early metastatic progression and expansion but down regulated during establishment and survival in metastatic nodes." (PMID 25629808, 2015). "Although many studies have related Ezrin with cancer metastasis and invasion, data also suggested that Ezrin may play a role in cancer by regulating the cell cycle." (PMID 26202611, 2015). "In addition, the value of ezrin expression as a prognostic biomarker is further consolidated in this type of cancer." (PMID 25278252, 2014). "Of note, ezrin as well as moesin can mediate the activation of ERK pathway in cancer cells." (PMID 25136657, 2014). "Stratified analysis of pooled hazard ratios of cancer patients with Ezrin expression." (PMID 23894313, 2013). "In invasive cancer cells, one could predict that the activated form of ezrin, phosphorylated on T567, would increase its relative expression in the organelle dedicated to invasion." (PMID 24086451, 2013). "Also of significance with regard to CRC invasion is the ability of Ezrin to function as a plasma membrane-actin cytoskeletal linker at the leading edge of invading cancer cells." (PMID 23755307, 2013). "Similarly, increased expression of the cytoskeletal linking protein ezrin is seen in endometrial hyperplasia and carcinoma." (PMID 23785665, 2013). "In contrast, Ezrin expression in the cancer cells was typically cytoplasmic." (PMID 23039327, 2012). "Interestingly, single scattered cancer cells or invasive cancer loci at the stroma frequently showed strongly and most intense immunoreactivity for Ezrin protein." (PMID 23039327, 2012). "Moreover, Y477F ezrin promotes formation of round colonies by carcinoma cells embedded in 3D Matrigel culture, compared to formation of invasive colonies by control cells." (PMID 22397367, 2012).
cancer (continued). "Furthermore, recent study demonstrated the co-operative effect of ezrin and c-Src, which also correlated with Pyk2, in cancer cells, in cancer cell metastases." (PMID 17551499, 2007). "The hub proteins, such as CCT4, EZR, and GAPDH, are known to be involved in critical pathways like neutrophil degranulation and sirtuin signaling, which are linked to the altered metabolic profiles and increased cancer stemness observed in neoadjuvant-treated PDAC." (PMID 40559993, 2025). "Similarly, other publication showed that Nudifloside, a derivative of Callicarpa nudiflora used in China as a traditional folk medicine, can reverse the EndMT (through inhibiting Ezrin phosphorylation) induced by TGFβ1 122, thus revealing a potential anti-EndMT drug for cancer therapy." (PMID 40083695, 2025). "The inhibition of ezrin phosphorylation may be an effective strategy for cancer treatment." (PMID 36355541, 2022). "Hence, designing inhibitors to interfere with the interaction of ezrin with related proteins may be another strategy for cancer therapy." (PMID 36355541, 2022). "Moreover, ezrin promotes invasion and metastasis of cancer cells." (PMID 34771571, 2021). "Thus, PD-L1 expression modulation in the plasma membrane of cancer cells by therapeutic agents targeting ezrin and/or radixin may represent a novel treatment strategy to boost the efficacy of PD-1/PD-L1 blockade therapies in CRC." (PMID 34577564, 2021). "Therefore, ezrin may exert multiple function not only in driving the MDR but also in acquiring metastatic phenotype of cancer cells in human tumors." (PMID 33974673, 2021). "Conversely, the incubation of C2C12 cells with Ori or Iru did not caused any detectable protection on Ezrin, suggesting that this protein may represent a target for the two compounds only in certain cancer cells." (PMID 33003361, 2020). "Therefore, Ezrin controls adhesion and the invasiveness of cancer cells through the interactions between cell adhesion molecules, suggesting a role in developing cervical neoplasia and cancer." (PMID 33240887, 2020). "In addition, we address Ezrin’s signaling pathways in cancer development and prognosis." (PMID 33240887, 2020). "Obtaining this kind of information will allow an extension of the established regulatory role of ezrin in the membrane vicinity towards a broader modulation of the whole-cell morphology and biophysical phenotypes that may then enable metastasis and cancer progression." (PMID 31936668, 2020). "Therefore, the specific role of Ezrin in different cancers remains to be elucidated." (PMID 29190988, 2017). "Ezrin activation and subsequent interaction with membrane proteins and the cytoskeleton may promote cell migration, invasion, adhesion, and survival, which are important for cancer progression." (PMID 29291001, 2017). "Therefore, Ezrin may serve as a new biomarker in these cancers to guide clinicians in choosing the most suitable treatment plans." (PMID 29190988, 2017). "Therefore, overexpression of ezrin as a result of Myc over expression could, in turn, maintain the survival of cancer cells through activation of the PI3K/Akt pathway." (PMID 26943769, 2016). "In addition, Ezrin is involved in migration of carcinoma cells, including NSCLC cells." (PMID 27344171, 2016). "Notably, Ezrin phosphorylation is necessary for cancer cell proliferation." (PMID 26202611, 2015). "Therefore, the prognostic value of Ezrin in cancer patients remains controversial." (PMID 26632332, 2015). "This meta-analysis suggests that Ezrin may be a potential prognostic marker in cancer patients." (PMID 26632332, 2015). "The overexpression and abnormal localization of ezrin, the founding member of the ezrin-radixin-moesin (ERM) family of membrane cytoskeletal crosslinkers, has been associated with positive LN status, metastasis, and poor outcome in various human cancers including breast." (PMID 25231728, 2014).
cancer (continued). "We believe that p-ezrin could serve as a marker potentially applicable to the detection and identification of pre-symptomatic cancers and, secondly, could be exploited as a therapeutic target in those cancers." (PMID 24086451, 2013). "Another group of differentially expressed proteins are associated with increased cancer cell motility and invasiveness, which include EphA2, BCAS1, S100 protein family members, Rho family members, Ral-A, Rab family members, Cdc42, MARCKS, Ezrin, Galectins 1 and 3 among others." (PMID 22417809, 2012). "Moreover, other members of ERM family, such as ezrin, function similarly as moesin in cancer cells." (PMID 20429915, 2010). "Proteins of the ezrin, radixin, and moesin (ERM) family are key regulators of cell morphogenesis and essential determinants of cancer cell metastasis." (PMID 41844278, 2026). "Notably, our earlier investigation into cancer invasion and metastasis proposed that the dynamic phosphorylation of ezrin at Thr567 may serve as an initial priming event, preparing the ezrin molecule for further post-translational modifications as the disease progresses." (PMID 40082743, 2025). "Given that ACAP4’s interaction with ezrin undergoes context-dependent conformational changes, it would be intriguing to explore whether and how the phosphorylation of ezrin at Ser567 interacts with Acapin phosphorylation to influence cancer metastasis using xenograft in the future." (PMID 40082743, 2025). "Next, the potential antineoplastic effects of the pharmacological ezrin inhibitor NSC305787 were investigated in cervical (A-431) and gastric (AGS and HGC-27) cancer cells." (PMID 38972247, 2024). "Ezrin (EZR), a member of the ezrin-radixin-moesin (ERM) cytoskeletal protein family, has been shown to participate in many aspects of cancer metastasis." (PMID 38540273, 2024). "Thus, targeting the phosphorylation of Ezrin may best prevent cancer progression." (PMID 37371090, 2023). "Ezrin plays a large role in EMT, which initiates the escape of cancer cells from their primary site and enhances their migratory capacity and invasiveness." (PMID 37371090, 2023). "The positive expression rates of Ezrin, YAP1, and CTGF in cancer tissues were 86.7, 91.6, and 88.3%, while corresponding adjacent tissues showed low expression rates of 23.3, 11.7, and 18.3%, respectively." (PMID 37791063, 2023). "We analyzed the relationship between differential Ezrin expression and ESCC cancer stage in patient data from the UALCAN database." (PMID 37791063, 2023). "The overexpression of S100P promotes cancer progression and metastasis through extracellular signaling via the RAGE receptor or through intracellular interaction with ezrin." (PMID 37583701, 2023). "Altogether, these data suggest that stimulation of cancer cells to develop invadopodia by plating on ECM occurs through the formation of a protein–protein complex formed by β1-integrin, ILK, p(T567)-ezrin, NHERF1 and NHE1." (PMID 33671549, 2021). "Ezrin is a cytoskeletal protein belonging to the Ezrin-Radixin-Moesin (ERM) family that plays an essential role in cell adhesion, motility, invasion, cancer progression, and metastasis." (PMID 34887447, 2021). "Moreover, Ki67, ezrin, and vimentin may serve as potential therapeutic targets in cancer." (PMID 34198671, 2021). "KEGG analysis identified adhesion, hematopoiesis and cancer-related proteoglycans as affected pathways (e.g. metformin: CD9, CTSL, IL5, HGF; insulin: EGF, EZR, PLCG2, TFRC)." (PMID 33690729, 2021). "The cytosolic protein Ezrin is a member of the ERM (Ezrin, radixin, moesin) protein family that promotes cancer cell migration and invasion." (PMID 33046994, 2020). "Similarly, and even though further studies are needed to understand the molecular mechanism in detail, our results suggest that ezrin phosphorylation might be a promising molecular target for cancer therapy, especially to suppress cancer invasion and metastasis." (PMID 31936668, 2020).